PRPF19 (pre-mRNA processing factor 19)
Description:
Ubiquitin-protein ligase which is a core component of several complexes mainly involved pre-mRNA splicing and DNA repair. Required for pre-mRNA splicing as component of the spliceosome. Core component of the PRP19C/Prp19 complex/NTC/Nineteen complex which is part of the spliceosome and participates in its assembly, its remodeling and is required for its activity. During assembly of the spliceosome, mediates 'Lys-63'-linked polyubiquitination of the U4 spliceosomal protein PRPF3. Ubiquitination of PRPF3 allows its recognition by the U5 component PRPF8 and stabilizes the U4/U5/U6 tri-snRNP spliceosomal complex. Recruited to RNA polymerase II C-terminal domain (CTD) and the pre-mRNA, it may also couple the transcriptional and spliceosomal machineries. The XAB2 complex, which contains PRPF19, is also involved in pre-mRNA splicing, transcription and transcription-coupled repair. Beside its role in pre-mRNA splicing PRPF19, as part of the PRP19-CDC5L complex, plays a role in the DNA damage response/DDR. It is recruited to the sites of DNA damage by the RPA complex where PRPF19 directly ubiquitinates RPA1 and RPA2. 'Lys-63'-linked polyubiquitination of the RPA complex allows the recruitment of the ATR-ATRIP complex and the activation of ATR, a master regulator of the DNA damage response. May also play a role in DNA double-strand break (DSB) repair by recruiting the repair factor SETMAR to altered DNA. As part of the PSO4 complex may also be involved in the DNA interstrand cross-links/ICLs repair process. In addition, may also mediate 'Lys-48'-linked polyubiquitination of substrates and play a role in proteasomal degradation. May play a role in the biogenesis of lipid droplets (By similarity). May play a role in neural differentiation possibly through its function as part of the spliceosome (By similarity).
Synonyms: hPso4; NMP200; PRP19; SNEV; UBOX4; PSO4
Tractability: Small molecule: a structure with a bound ligand is known. PROTAC: ubiquitination databases record sites on it; its protein half-life has been measured.
Target class: Enzyme; Transferase
Gene: Protein-coding gene on chromosome 11 (60,890,547 to 60,906,603, reverse strand). Ensembl gene ENSG00000110107.
Subcellular location: Nucleus; Nucleus, nucleoplasm; Cytoplasm, cytoskeleton, spindle; Cytoplasm; Lipid droplet
Subcellular location (Human Protein Atlas): Nuclear speckles
Pathways (Reactome):
DNA Repair: Dual incision in TC-NER; Formation of TC-NER Pre-Incision Complex; Gap-filling DNA repair synthesis and ligation in TC-NER; Transcription-Coupled Nucleotide Excision Repair (TC-NER)
Disease: Dengue Virus-Host Interactions
Metabolism of RNA: mRNA Splicing - Major Pathway
Gene Ontology:
Molecular function: identical protein binding; protein binding; ubiquitin protein ligase activity; ubiquitin-ubiquitin ligase activity; ubiquitin-protein transferase activity
Biological process: DNA damage checkpoint signaling; double-strand break repair via nonhomologous end joining; intracellular protein localization; mRNA splicing, via spliceosome; proteasomal protein catabolic process; protein K63-linked ubiquitination; protein polyubiquitination; spliceosomal complex assembly; spliceosomal tri-snRNP complex assembly; protein ubiquitination
Cellular component: catalytic step 2 spliceosome; cytoplasm; DNA replication factor A complex; membrane; nuclear speck; nucleus; post-mRNA release spliceosomal complex; post-spliceosomal complex; Prp19 complex; site of double-strand break; spliceosomal complex; U2-type catalytic step 1 spliceosome; U2-type catalytic step 2 spliceosome; nucleoplasm; lipid droplet; spindle
Genetic constraint (gnomAD): Loss-of-function variants: 2 observed, 63.85 expected, observed/expected ratio (o/e) 0.0313, 90% interval 0.012 to 0.099. The upper end of that interval is the gene's LOEUF score, 0.099, which puts it in group 1 of 6, group 1 being the genes least tolerant of losing a copy. Missense variants: 314 observed, 657.44 expected, observed/expected ratio (o/e) 0.48, 90% interval 0.44 to 0.52. Synonymous variants: 226 observed, 255.05 expected, observed/expected ratio (o/e) 0.89, 90% interval 0.79 to 0.99.
Homologues: Orthologues: rabbit PRPF19 (100% identical), guinea pig PRPF19 (99% identical), mouse Prpf19 (99% identical), pig PRPF19 (99% identical), rat Prpf19 (99% identical), dog PRPF19 (99% identical), macaque PRPF19 (99% identical), chimpanzee PRPF19 (98% identical), zebrafish prpf19 (85% identical), tropical clawed frog prpf19 (84% identical), Drosophila melanogaster Prp19 (66% identical), Caenorhabditis elegans prp-19 (51% identical). Paralogues in human: WDR36 (21% identical).
Diseases named in the same sentence as PRPF19 in open-access papers:
PRPF19 is named in the same sentence as 43 diseases in open-access papers, as found by Europe PMC text mining. Sharing a sentence is not in itself a finding about the gene and the disease. The quoted sentences say what the papers report.
hepatocellular carcinoma (16 papers, 2014 to 2024). A malignant tumor that arises from hepatocytes. "A research investigation revealed an upregulation of PRPF19 expression in hepatocellular carcinoma, which exhibited a strong association with worse disease prognosis." (PMID 38022515, 2023). "A cell type-dependent context of PRPF19 action on cellular senescence was also recently observed in liver carcinoma cells, where its overexpression as a myc-tag fusion protein resulted in induction of senescence, similarly as in our fibroblast experiments." (PMID 37214773, 2023). "However, the biological role of PRPF19 in hepatocellular carcinoma (HCC) is still elusive." (PMID 35252202, 2022). "The increased PRPF19 detected in tissues and cell lines of hepatocellular carcinoma (HCC) have been reported; the authors also found that HCC patients with high expression of PRPF19 had a shorter OS than those with a lower expression of PRPF19." (PMID 35252202, 2022).
breast carcinoma (5 papers, 2009 to 2025). "The Mann-Whitney U test showed that five AAbs (HSPA4, PRPF19, ENO1, PRDX6, and MMP14) were significantly higher in the breast cancer group than in the control group." (PMID 40766308, 2025). "We validated these five autoantibodies (HSPA4, ENO1, PRDX6, PRPF19, and MMP14) in an independent cohort of 33 breast cancer patients and 45 healthy controls." (PMID 40766308, 2025). "Anti-HSPA4, anti-PRPF19, anti-ENO1, anti-PRDX6, and anti-MMP14 autoantibodies showed significant increases in breast cancer patients." (PMID 40766308, 2025). "In the verification cohort, IgG autoantibodies against HSPA4, ENO1, PRDX6, PRPF19 and MMP14 were significantly increased in breast cancer patients with areas under the curve (AUCs) of 0.90, 0.89, 0.82, 0.78 and 0.77, respectively." (PMID 40766308, 2025). "Five potential AAb biomarkers (HSPA4, ENO1, PRDX6, PRPF19, MMP14) predictive of breast cancer were identified through verification and validation cohorts." (PMID 40766308, 2025).
bladder cancer (4 papers, 2022 to 2025). "We investigated the relevance of PRPF19 to senescence-associated secretory phenotype (SASP)-related genes in bladder cancer." (PMID 38022515, 2023). "Nevertheless, there exists a deficiency of research on the correlation between PRPF19 and bladder cancer, leading to the need for further study." (PMID 38022515, 2023). "In this work, an investigation was conducted to examine the correlation between PRPF19 and genes linked to senescence-associated secretory characteristics across several bladder cancer datasets." (PMID 38022515, 2023). "Initially, a comparative analysis of PRPF19 mRNA expression was conducted in bladder cancer and normal bladder tissues using the TCGA and GEO databases." (PMID 38022515, 2023). "In summary, our findings have substantiated the elevated expression of PRPF19 in bladder cancer and established its potential use as a predictive biomarker for individuals diagnosed with this malignancy." (PMID 38022515, 2023). "In the context of paired bladder cancer tissue samples, it was shown that the expression of PRPF19 was markedly elevated compared to normal bladder tissue." (PMID 38022515, 2023). "In order to investigate the probable mechanism behind the oncogenic involvement of PRPF19 in bladder cancer, a gene enrichment analysis was conducted." (PMID 38022515, 2023). "In summary, our study provides evidence that PRPF19 has a substantial impact on the immunological environment of bladder cancer and has the potential to serve as a prognostic indicator in patients afflicted with this condition." (PMID 38022515, 2023). "This study analysed the role of PRPF19 in bladder cancer prognosis as well as in the immune microenvironment from several perspectives, but threw some limitations." (PMID 38022515, 2023). "This work aimed to investigate the variations in PRPF19 expression in bladder cancer by using the BLCA dataset from the TCGA database, as well as the GSE13507 and GSE120736 datasets from the GEO database." (PMID 38022515, 2023). "The findings from the KEGG analysis demonstrate that PRPF19 has a regulatory role in several aspects of bladder cancer cell biology, including senescence, cell cycle progression, and resistance to platinum-based drugs." (PMID 38022515, 2023). "The results showed a significant increase in PRPF19 mRNA expression in bladder cancer tissues compared to normal bladder tissues." (PMID 38022515, 2023). "The UALCAN database was used to assess the presence of a statistically significant difference in PRPF19 methylation levels between bladder cancers and normal bladder tissues." (PMID 38022515, 2023). "The difference in PRPF19 expression between bladder cancer and normal bladder cancer samples was shown by the use of box plots." (PMID 38022515, 2023). "PRPF19 mRNA levels were significantly higher in bladder cancer samples compared to paired paraneoplastic tissues in the TCGA bladder cancer dataset." (PMID 38022515, 2023). "The SMART database was employed for analysis in order to investigate the involvement of PRPF19 methylation in bladder cancer." (PMID 38022515, 2023). "Notable alterations were seen in the expression of PRPF19 mRNA when comparing low-grade and high-grade bladder cancer samples." (PMID 38022515, 2023). "Gene set enrichment analysis (GSEA) offered more elucidation into the role of PRPF19 in the context of bladder cancer." (PMID 38022515, 2023). "The results of this analysis provided confirmation that PRPF19 serves as a valuable predictive biomarker for patients with bladder cancer." (PMID 38022515, 2023). "In the TCGA-BLCA dataset, samples from patients with bladder cancer were classified into high-expression and low-expression groups of PRPF19, based on the level of PRPF19 expression." (PMID 38022515, 2023). "In the present investigation, it was shown that there were significant variations in the methylation levels of PRPF19 between bladder cancer and normal bladder tissue." (PMID 38022515, 2023).
bladder cancer (continued). "In this study, we utilized transcriptomic data and bladder cancer tissue microarrays to identify the high expression of PRPF19 in BLCA, suggesting its potential as a prognostic biomarker." (PMID 38022515, 2023). "The present study used Oncoplot to visually represent the somatic landscape of the TCGA bladder cancer cohort, whereby samples were classified into high and low PRPF19 expression categories." (PMID 38022515, 2023). "Our observations reveal a noteworthy elevation in PRPF19 expression in bladder cancer tissues as against normal bladder tissues." (PMID 38022515, 2023). "A set of 56 bladder cancer tissue samples and 32 normal bladder tissue samples were analyzed to further assess the expression and prognostic significance of PRPF19." (PMID 38022515, 2023). "Our analysis revealed that PRPF19 exhibited elevated expression levels in bladder cancer, with a notable increase seen in higher-grade tumors." (PMID 38022515, 2023). "Correlation analysis of PRPF19 with pathological parameters of bladder cancer." (PMID 38022515, 2023). "Additionally, an investigation was conducted to examine the impact of PRPF19 on bladder cancer stem cells." (PMID 38022515, 2023). "The purpose of this study was to investigate the potential involvement of PRPF19 in bladder cancer." (PMID 38022515, 2023). "We also looked into how methylation of PRPF19 affects bladder cancer." (PMID 38022515, 2023). "Additionally, it was shown that PRPF19 had a significant correlation with both the secretory phenotype often seen in senescence and the stemness characteristics of bladder cancer cells." (PMID 38022515, 2023). "COX regression analysis of the prognostic correlation between PRPF19 and bladder cancer." (PMID 38022515, 2023). "Hence, we conducted a more comprehensive examination of PRPF19 expression in bladder cancer by the utilization of methylation probes that possess predictive significance in this particular malignancy." (PMID 38022515, 2023). "We only confirmed the expression and prognostic value of PRPF19 in bladder cancer by bladder cancer tissue microarrays, and further experimental analysis of the role of PRPF19 and the immune microenvironment of bladder cancer is necessary, which will be further explored in our subsequent studies." (PMID 38022515, 2023). "It is plausible that PRPF19 methylation may exert its influence on bladder cancer via the involvement of cg26375147." (PMID 38022515, 2023). "The MHC pathway was discovered by our research team as a potentially significant channel by which PRPF19 may exert regulatory control on the immune microenvironment in cases of bladder cancer." (PMID 38022515, 2023). "This suggests that PRPF19 exerts an oncogenic function in the context of bladder cancer." (PMID 38022515, 2023). "Therefore, it is plausible that PRPF19 might potentially have an impact on other genetic modifications and function as a prognostic indicator for persons afflicted with bladder cancer." (PMID 38022515, 2023). "The TCGA bladder cancer dataset revealed a significant correlation between the expression levels of CCL16 and PRPF19 (r=0.166)." (PMID 38022515, 2023). "We obtained the results of immunohistochemical staining of PSMD14, PRPF19, PSMB5, and TPR in normal tissues and bladder cancer tissues and demonstrated that these four genes were highly expressed in tumor tissues and lowly expressed in normal tissues." (PMID 35898492, 2022). "In our investigation, it was shown that there exists a negative correlation between cg26375147 and PRPF19 in the context of bladder cancer." (PMID 38022515, 2023). "There exists a potential regulatory relationship between PRPF19 and CCL16, which may contribute to the promotion of stemness in bladder cancer cells." (PMID 38022515, 2023).
gastric cancer (3 papers, 2016 to 2025). A primary or metastatic malignant neoplasm involving the stomach. "PRPF19 expression was found to be greater in gastric cancer tissues and/or metastatic lymph nodes than in peri-cancerous tissues." (PMID 28122348, 2017).
neuroblastoma (3 papers, 2020 to 2022). Neuroblastoma (NB) is the most common solid, extracranial childhood tumor. "PRPF19 can enhance the invasive ability of neuroblastoma cells by regulated Hippo-YAP pathway, and this has been recently proposed in literature." (PMID 35252202, 2022).
Spinocerebellar ataxia type 3 (3 papers, 2021 to 2024). "Interestingly, acting through Prpf19, EXOC7 counteracts the degradation of polyQ aggregation and mediates toxicity in spinocerebellar ataxia type 3 (SCA3)." (PMID 37085629, 2023).
tongue cancer (2 papers, 2022 to 2024). A malignant neoplasm affecting the tongue. "Furthermore, upregulated Pre-mRNA Processing Factor 19 (PRPF19) expression is associated with poorer outcomes in tongue cancer patients." (PMID 39668816, 2024).
acute leukemia (1 paper, 2021). A clonal (malignant) hematopoietic disorder with an acute onset, affecting the bone marrow and the peripheral blood. "Through this approach, we have discovered three novel KMT2A translocation partners in childhood acute leukemia—genes encoding tyrosine kinase BTK, ubiquitin-protein ligase PRPF19, and NUTM2A—gene of poorly known function." (PMID 34440129, 2021).
asthma (1 paper, 2012). "Strong and direct association was found between rs7928208 in the PRPF19 gene and asthma and this SNP was also associated with asthma development before 6 years of age." (PMID 22432035, 2012). "The posterior that rs7928208 (PRPF19) is transitively associated to asthma is 0.822, and the posterior for a “direct” relation, which is not blocked by any other variable, is similarly high (0.718; RA dataset, asthma as a target variable)." (PMID 22432035, 2012). "The SNP rs7928208 in the gene PRPF19 is also associated with early childhood asthma (in case of children under 6 years)." (PMID 22432035, 2012). "Altogether 5 SNPs in 4 genes were found relevant in connection with asthma phenotype: PRPF19 on chromosome 11, and FRMD6, PTGER2 and PTGDR on chromosome 14." (PMID 22432035, 2012). "In the BN-BMLA analysis altogether 5 SNPs in 4 genes were found relevant in connection with asthma phenotype: PRPF19 on chromosome 11, and FRMD6, PTGER2 and PTGDR on chromosome 14." (PMID 22432035, 2012). "We compared the gene expression levels of genes found to be relevant in asthma in the SNP analysis in sputum samples of 12 asthmatics and 9 controls using TaqMan Gene Expression Assays (FRMD6, PTGDR, PTGER2, MS4A2, AHNAK, PRPF19, TXNDC16)." (PMID 22432035, 2012).
bladder tumors (1 paper, 2023). "It was observed that a difference existed between the methylation levels of PRPF19 in bladder tumors and normal bladder tissues." (PMID 38022515, 2023). "Specifically, the methylation levels of PRPF19 were shown to be much lower in bladder tumors compared to normal bladder tissues." (PMID 38022515, 2023). "Additionally, it was shown that the methylation levels of PRPF19 in bladder tumors of stages N0-3 were significantly lower compared to those in normal bladder tissue." (PMID 38022515, 2023). "Furthermore, an examination was conducted to assess the significance of PRPF19 in relation to bladder tumor stem cells." (PMID 38022515, 2023). "Hence, it is postulated that PRPF19 potentially modulates the stemness of bladder tumor cells by influencing the expression of the senescence-associated secretory phenotype-associated gene CCL16." (PMID 38022515, 2023).
colorectal cancer (1 paper, 2023). A primary or metastatic malignant neoplasm that affects the colon or rectum. "The mRNA and protein expression levels of PRPF19 were also markedly increased in tumor tissues compared with that in normal tissues in both rectal cancer and colorectal cancer." (PMID 37031206, 2023).
endometriosis (1 paper, 2025). The growth of functional endometrial tissue in anatomic sites outside the uterine body. "In the merged dataset, the expression levels of these six genes—DDR2, ENO3, ESM1, NMBR, PRKAB1, and PRPF19—showed significant differences between normal and endometriosis samples (DDR2, p < 0.001; ENO3, p < 0.001; ESM1, p < 0.001; NMBR, p = 0.002; PRKAB1, p < 0.001; PRPF19, p < 0.001)." (PMID 41424583, 2025).
epilepsy (1 paper, 2023). A brain disorder characterized by episodes of abnormally increased neuronal discharge resulting in transient episodes of sensory or motor neurological dysfunction, or psychic dysfunction. "In conclusion, due to the vital role that PRPF19 plays in neural differentiation and in DNA damage and repair, it could be hypothetically related to alterations found in certain types of epilepsy." (PMID 36980356, 2023).